MTOR (mechanistic target of rapamycin kinase)
Diseases named in the same sentence as MTOR in open-access papers (continued):
Sharing a sentence is not in itself a finding about the gene and the disease.
psoriasis (continued). "As a result, epidermal keratinocyte hyperproliferation contributes to the development of psoriasis by keeping the PI3K/Akt/mTOR pathway upregulated." (PMID 35163615, 2022). "Rapamycin, a first-generation mTOR inhibitor, has been studied in psoriasis patients for its antiproliferative and immunosuppressive characteristics." (PMID 35163615, 2022). "The use of mTOR inhibitors in psoriasis has been encouraged by studies indicating the upregulation of PI3K/Akt/mTOR pathway in psoriatic plaques and around the lesional skin." (PMID 35163615, 2022). "In this study, we found that fisetin directly modulates the transcription of the components of the mTORC1 (Raptor), and mTORC2 (Rictor) as well as Deptor, and other effector components of the mTOR signaling pathway, which are overexpressed in psoriasis." (PMID 36741386, 2022). "A study on peripheral blood gene sequencing of psoriasis patients found that mTOR methylation was significantly enhanced, suggesting that the mTOR gene is closely related to the pathogenesis of psoriasis." (PMID 36618400, 2022). "Inflammatory cytokines, including IL-22, IL-17, TNF-α can induce the aberrant activation of mTOR cascade in keratinocytes, leading to enhanced keratinocyte proliferation and reduced differentiation, which are the hallmarks of psoriasis." (PMID 35938153, 2022). "Aberrant PI3K/AKT/mTOR signaling is also observed in pathological skin, in particular in cutaneous cancer, as well as in chronic inflammatory diseases, such as psoriasis and atopic dermatitis (AD)." (PMID 33996865, 2021). "Dysregulation of PI3K/AKT/mTOR pathway in skin contributes to several pathological conditions characterized by uncontrolled proliferation, including skin cancers, psoriasis, and atopic dermatitis (AD)." (PMID 33996865, 2021). "Recently, the PI3K/Akt/mTOR pathway was reported to function in Th1/Th2/Th17 imbalance, which is key in the occurrence and development of psoriasis." (PMID 34067630, 2021). "The Akt/mTOR activation and STAT3 signaling are known to promote acanthosis, which is implicated in the immunopathogenesis of psoriasis." (PMID 33849555, 2021). "The role of PI3K/AKT/mTOR in AD is less characterized than in psoriasis, even though some evidences have accumulated so far." (PMID 33996865, 2021). "Up-regulation of PI3K/AKT/mTOR pathway has been reported in skin of patients affected by psoriasis, as well as in skin of imiquimod (IMQ)-induced psoriasiform mouse model." (PMID 33996865, 2021). "mTOR inhibitor topicals are already used for psoriasis treatment in corticosteroid-sensitive areas, such as genitals and face." (PMID 33921372, 2021). "The PI3K/AKT/mTOR activation and STAT3 signaling are known to promote acanthosis, which is implicated in the immunopathogenesis of psoriasis." (PMID 34834106, 2021). "The Th1/Th2/Th17 imbalance activates PI3K/AKT/mTOR pathway and results in the occurrence and development of psoriasis." (PMID 34834106, 2021). "In conclusion, we have established that downregulation of lncRNA H19 promoted the proliferation of keratinocytes and skin inflammation by up-regulating miR-766-3p expression levels and inhibiting activation of S1PR3 through the AKT/mTOR pathway in psoriasis." (PMID 34992498, 2021). "Concomitantly, the JAK/STAT signal transduction pathway and the PI3K/AKT/mTOR signaling pathway are also involved in psoriasis development and progression." (PMID 34834106, 2021). "We established that downregulation of lncRNA H19 promoted the proliferation of keratinocytes and skin inflammation by up-regulating miR-766-3p expression levels and inhibiting activation of S1PR3 through the AKT/mTOR pathway in psoriasis." (PMID 34992498, 2021). "IL-22-induced keratinocyte hyperproliferation is regulated by the PI3K/Akt/mTOR signaling pathway, and targeting this pathway is a potent approach for psoriasis treatment." (PMID 33149756, 2020).
psoriasis (continued). "In several studies, it has been demonstrated that IL-17A significantly enriched the mTOR pathway and mediated the proliferation of fibroblast-like synovial cells by mediating this pathway and inflammatory responses in psoriasis." (PMID 33099538, 2020). "The JNK and AKT/mTOR signaling pathways have been shown to be involved in the pathogenesis and progression of psoriasis." (PMID 31357564, 2019). "Regulatory T-cells from psoriasis patients show increased mTOR phosphorylation and treatment with methotrexate reduces mTOR activation." (PMID 30555471, 2018). "In contrast, in psoriasis overexpression of Th17 cytokines induces strong activation of mTOR signaling which prevents keratinocytes from proper differentiation in order to form the correctly stratified epidermis." (PMID 28700632, 2017). "This contributed to the induction and/or maintenance of the psoriatic phenotype through the initiation of proliferation and blockade of proper differentiation, thus pointing towards mTOR as a potential target for therapeutic intervention in psoriasis." (PMID 28700632, 2017). "In contrast, under inflammatory conditions such as psoriasis, cytokines induced aberrant activation of the mTOR cascade." (PMID 28700632, 2017). "Rapalogs, next-generation mTOR inhibitors, and novel plant-derived phytochemicals thus continue to be investigated as possible mTOR-based psoriasis treatments." (PMID 26251673, 2015). "Within psoriasis lesions, mTOR kinase is elevated throughout the epidermis and activated phospho-mTOR (Ser2448) is prominent in the basal layer." (PMID 26251673, 2015). "Nevertheless, mTOR signalling is hyper-activated in psoriatic lesions and altered expression of RPTOR may contribute to psoriasis susceptibility." (PMID 39145956, 2024). "Our findings suggest that limonin exerts anti-inflammatory effects on psoriatic skin lesions by restoring the altered metabolic program under psoriasis-like inflammatory conditions, downregulating the mTOR signaling pathway, and inhibiting mitochondrial ROS production." (PMID 39765869, 2024). "Thus, targeting the downregulated Sema4A and upregulated mTOR signaling in psoriatic epidermis can be a promising strategy for psoriasis therapy and modification of psoriatic diathesis in NL for the prevention of disease development." (PMID 39737847, 2024). "Together these results suggest that small molecule inhibitors which block CARD14 activation of mTORC1 (e.g. PI 3-kinase, Akt or mTOR inhibitors) may have beneficial therapeutic effects in psoriasis in combination with an anti-inflammatory drug." (PMID 39145956, 2024). "Furthermore, TNF and mTOR signaling pathways, which play a role in the pathogenesis of psoriasis, were among the major disease-residual pathways identified in our STRING and KEGG pathway analyses." (PMID 36901987, 2023). "Hematology data demonstrated the safety of using these biomaterials, which provide a potential therapeutic-option for psoriasis treatment due to desirable effects, especially anti-proliferation and anti-inflammation, functioning via the mTOR pathway and control of IL-17 signaling." (PMID 37495626, 2023). "Additionally, we evaluated the effects of PSORI-CM02 and BPTES, an mTOR inhibitor, on the hyperproliferation of epidermal keratinocytes in the imiquimod-induced psoriasis mouse (IMQ) model." (PMID 37089953, 2023). "Rapamycin, a well-known mTOR inhibitor, alleviated psoriasis-like dermatitis by inducing autophagy." (PMID 36937834, 2023). "Matrine was reported to inactivate the PI3K/Akt/mTOR pathway, mitigating psoriasis symptoms." (PMID 37371141, 2023). "In addition, control of amino acids or inhibition of mTOR can prevent the activation of immune cells and the differentiation of keratinocytes in psoriasis." (PMID 37649889, 2023). "Notably, mTOR kinase, a downstream effect of this pathway, is over-activated during the course of psoriasis pathology, promoting keratinocyte proliferation and suppressing differentiation." (PMID 37631075, 2023).
psoriasis (continued). "Considering these data, we sought to determine whether AMPK/mTOR is the signaling pathway involved in serine metabolism regulated by AOA regulates in psoriasis." (PMID 37649889, 2023). "Therefore, the modulation of proinflammatory cytokine secretion and altered Akt/mTOR signaling is an attractive avenue to discover therapies for skin cancer and inflammatory skin diseases, including eczema, seborrheic dermatitis, and psoriasis." (PMID 38102220, 2023). "Additionally, when the immune-mediated inflammatory state of psoriasis is dysregulated, mTOR signaling is activated in keratinocytes." (PMID 37631075, 2023). "The mTOR signaling cascade in psoriasis has been well recognized for decades." (PMID 37495626, 2023). "In patients with psoriasis, the mTOR signaling pathway may be abnormally activated, leading to abnormal proliferation of skin cells and over-activation of the immune system." (PMID 38239345, 2023). "Therefore, researchers have begun to explore mTOR inhibitors as a potential strategy for the treatment of psoriasis." (PMID 38239345, 2023). "Suppression of PI3K/AKT/mTOR (mammalian target of rapamycin) signaling has also been suggested in the treatment of psoriasis and the antioxidant protein, HO-1, may mitigate IMQ-induced psoriasis-like inflammation by blocking the STAT3 signal." (PMID 35720176, 2022). "The role of mTOR is less investigated in rosacea than in AD and psoriasis." (PMID 35938153, 2022). "PI3K/AKT/mTOR over-expression may contribute to uncontrolled proliferation in skin disorders, including skin cancers, psoriasis, and atopic dermatitis." (PMID 35428182, 2022). "Subsequently, we demonstrated that TC could regulate IL-17A-induced inflammation and cell proliferation via the mTOR/p70S6K and NF-κB signaling pathways and, thus, may play a role in the pathogenesis of psoriasis." (PMID 36498953, 2022). "Topical administration of fisetin in an imiquimod (IMQ)-induced mouse psoriasis model exhibited a better effect than rapamycin in reducing psoriasis-like inflammation and Akt/mTOR phosphorylation and promoting keratinocyte differentiation and autophagy in mice skin lesions." (PMID 36741386, 2022). "Therefore, suppression of keratinocyte hyperproliferation, T-lymphocyte activation as well as the release of their proinflammatory mediators while inhibiting the activation of the central mTOR have proven to be useful clinical anti-psoriasis strategies." (PMID 36741386, 2022). "The PI3K/AKT/mTOR signaling pathway is widely involved in the proliferation of various types of cells, and also plays an important role in regulating development and progression of autoimmune diseases including psoriasis." (PMID 36618400, 2022). "Moreover, fisetin inhibits the release of proinflammatory cytokines by activated peripheral blood mononuclear cells (PBMCs) and keratinocytes, and the activation of PI3K/Akt/mTOR/MAPK in in vitro models of psoriasis." (PMID 36741386, 2022). "LncRNA H19 might serve as a sponge for miR-766-3p to up-regulate S1PR3 levels and regulates the proliferation of keratinocytes and skin inflammation by AKT/mTOR pathway in psoriasis." (PMID 34992498, 2021). "Moreover, BCAA supplementation suppresses Akt2 activation through mTORC1- and mTORC2-dependent pathways 44, and NF-κB and mTOR are therapeutic targets of psoriasis." (PMID 33391503, 2021). "Moreover, research has shown that mTOR was involved in the occurrence of inflammatory skin diseases such as psoriasis and acne and the mTOR signaling pathway participates in the occurrence of malignancies in multiple systems." (PMID 34874800, 2021). "Moreover, excessive ROS from UV activate PI3K/Akt/mTOR (mammalian target of rapamycin) pathway to initiate several cutaneous diseases like psoriasis, MM and chloasma, therefore considering this pathway as a pivotal target for these dermatoses treatment." (PMID 34355664, 2021).
psoriasis (continued). "It has also been reported that the dysregulation of cytokines and growth factors like IL-17 and IL-12 could activated the mTOR pathway, which is an essential factor to regulate the proliferative and inflammatory process in psoriasis." (PMID 34067630, 2021). "The role of PI3K/AKT/mTOR in AD is less characterized than in psoriasis." (PMID 33996865, 2021). "Ribosomal protein S6, which is both a key mediator of mTOR function and coordinate regulator of ribosome function and biogenesis, is hyperactivated and abnormally phosphorylated in epidermal lesions of patients with psoriasis." (PMID 34344401, 2021). "Due to the pleiotropic effect of mTOR in different tissues and the autophagic effect recently described, it could be a new research line to further comprehend psoriasis-related endotypes." (PMID 33921372, 2021). "Recently, the mTOR signaling has emerged as an important player in the pathogenesis of psoriasis." (PMID 33921372, 2021). "The inhibition of the PI3K-Akt-mTOR pathway alleviates the psoriasis symptoms." (PMID 32377228, 2020). "AKT2 participates in the PI3K/AKT/mTOR signaling pathway as a critical mediator in psoriasis." (PMID 32411787, 2020). "It has been shown that mTOR signaling plays a critical role in psoriasis pathogenesis." (PMID 32908937, 2020). "mTOR inhibitors have been tested in the animal models and clinics for the treatment of psoriasis." (PMID 32908937, 2020). "Then, growth factors and relevant cytokines (IL-17A, TNF-α, and IL-1β) in psoriasis activate mTOR and promote keratinocyte hyperproliferation and inhibit differentiation, which might be the mechanism underlying the PI3K/Akt pathway and psoriasis." (PMID 31824416, 2019). "Recent studies show that the AKT/mTOR signaling pathway is highly activated in human psoriasis, which means that inhibition of the AKT/mTOR signaling pathway may act a potential therapeutic strategy for psoriasis." (PMID 31357564, 2019). "As they are efficiently inhibiting both mTOR complexes and thus inhibit Akt signaling, they could be interesting therapeutic compounds in psoriasis." (PMID 30555471, 2018). "It is currently hypothesized that the PI3-K/Akt/mTOR cascade plays a role in the pathogenesis of psoriasis by regulating the function of immune cells as well as intrinsic alterations within the epidermis." (PMID 28700632, 2017). "Previous studies have highlighted activation of the mammalian target of rapamycin (mTOR)/S6K pathway in psoriasis lesions, although our findings suggest that mechanisms governing hyper-translation in psoriasis are broader, involving proteins besides the canonical mTOR targets." (PMID 26251673, 2015). "Thus, inhibiting PI3K/Akt/mTOR signalling was a suitable approach to psoriasis therapy." (PMID 40989584, 2025). "Metformin is also an mTOR inhibitor and promotes the conversion of T helper 17 (Th17) cells to regulatory T (Treg) cells through enhanced autophagic processes, suggesting its potential therapeutic application in psoriasis management through the modulation of type 17-mediated inflammation." (PMID 40332377, 2025). "Importantly, the therapeutic targeting of these pathways shows promise, as evidenced by rapamycin, an mTOR inhibitor widely used in clinical practice, which has demonstrated therapeutic potential in both cellular and animal models of psoriasis through its inhibition of the mTOR pathway." (PMID 40332377, 2025). "In addition, a case report also showed that the combination of mTOR inhibitors including everolimus and tacrolimus could treat recalcitrant psoriasis." (PMID 40332377, 2025). "The miR-424-5p/AKT/mTOR axis may also be a potential target for psoriasis therapy." (PMID 40725772, 2025). "Furthermore, mTOR activation has been linked with the transition from psoriasis to non-skin manifestations such as psoriatic arthritis and cardiovascular events." (PMID 38928483, 2024).
psoriasis (continued). "However, the use of mTOR inhibitors is accompanied by a number of potential side effects and safety concerns, so further research is needed to determine the best treatment options and for which psoriasis patients." (PMID 38239345, 2023). "Interestingly, HIF-1α/mTOR-mediated glycolysis contributes to the activation and proliferation of lymphocytes as well, suggesting a potential role for targeting this axis in the suppression of psoriasis progression." (PMID 37089953, 2023). "Despite the fact that inhibitors of mTOR have been employed in the treatment of various dermatologic disorders such as Kaposi sarcoma, tuberous sclerosis, Muir-Torre syndrome, and neurofibromatosis, their effects on psoriasis have been investigated only in a small number of case reports." (PMID 35163615, 2022). "Thus, oral and topical mTOR inhibitors may be a successful therapeutic strategy in psoriasis and further research exploring the role of mTOR pathway as therapeutic target is warranted." (PMID 35265634, 2022). "Consequently, we hypothesized that dual inhibition of immune cells and targeting the mTOR/autophagy arm with a single natural product would alleviate the psoriasis-like phenotype of IMQ-induced mice." (PMID 36741386, 2022). "In addition, these cytokines upregulate PI3K/AKT/mTOR pathway, which in turn controls secretion of pro-inflammatory mediators by keratinocytes, enhances proliferation and impairs keratinocyte differentiation in skin affected by psoriasis." (PMID 33996865, 2021). "Signaling pathways, known to be implicated in psoriasis development, are the Janus kinase/signal transducer and activator of transcription (JAK/STAT), the nuclear factor kappa B (NF-κB) and the phosphatidylinositol 3-kinase/protein kinase B/mammalian target of rapamycin (PI3K/AKT/mTOR) pathway." (PMID 34834106, 2021). "Finally, elevated levels of ROS observed during the development of psoriasis may suppress AKT phosphorylation, which, by inhibiting the mammalian target of rapamycin (mTOR) pathway, causes autophagy activation." (PMID 33066703, 2020). "Moreover, interactions between IL-17A and the PI3K/AKT/mTOR signaling pathway were investigated in several diseases: the effect on autophagy in psoriasis; induced proliferation and migration of glioma cells; the role of lipopolysaccharide (LPS)-induced acute lung injury, etc.." (PMID 33099538, 2020). "However, our data support the notion that psoriasis patients could rather benefit from the topical use of mTOR inhibitors on the affected skin, which showed encouraging results in a small trial." (PMID 28700632, 2017). "The anti-proliferative mechanisms of natural products in the treatment of psoriasis are primarily centered on the modulation of critical signaling pathways, including NF-κB, PI3K/Akt/mTOR, and various cell cycle regulators." (PMID 40690118, 2025). "A pivotal finding demonstrates the critical role of autophagy dysfunction in psoriasis, wherein IL-17A mediates autophagy suppression via the PI3K/AKT/mTOR pathway, establishing a fundamental link between inflammatory signaling and cellular homeostasis." (PMID 40332377, 2025). "Multi-omics identifies the activation of the PI3 K/AKT/mTOR and JAK-STAT pathway in 76% of psoriasis lesions; FABP5 overexpression (1.8-fold vs. normal skin) is a potential therapeutic target." (PMID 41293553, 2025). "Then use the prepared diosmin nanocrystals gel topically in 3 different concentrations to evaluate its efficacy in alleviating IMQ induced psoriasis in rats via modulating TLR7,8/NF-κB/micro RNA-31, AKT/mTOR/P70S6K milieu and Tregs/Th17 balance." (PMID 37010718, 2023). "T-cells derived from patients with psoriasis have been reported to have amplified receptors and increased activities for the PI3K/Akt/mTOR pathway in psoriatic skin lesions." (PMID 37371141, 2023). "Other signaling pathways identified to be deregulated in psoriasis, such as STAT1/3, AMPK, Ras/MAPK, and NF-κB, also directly or indirectly activate mTOR." (PMID 37371141, 2023).